SMO (smoothened, frizzled class receptor)
Diseases named in the same sentence as SMO in open-access papers (continued):
Sharing a sentence is not in itself a finding about the gene and the disease.
arteriovenous malformations (1 paper, 2025). "While the direct role of SMO in vascular malformations like arteriovenous malformations (AVMs) is not fully understood, the Hedgehog pathway has been shown to influence vascular development and remodeling." (PMID 40564170, 2025).
Bardet-Biedl syndrome (1 paper, 2020). A ciliopathy with multisystem involvement. "Patched 1, GPR161, SMO and other ciliary membrane proteins are all ferried out of cilia in a regulated manner by an evolutionarily conserved complex of eight Bardet-Biedl Syndrome (BBS) proteins, the BBSome." (PMID 32510327, 2020).
bone tumors (1 paper, 2019). "Cartilage/bone tumors often show activated Hh signaling, resulted either from mutations in EXT1/2, PTH1R, or SMO or from elevated expression of hedgehog ligands or Gli proteins." (PMID 31482846, 2019).
brain cancer (1 paper, 2019). A primary or metastatic malignant neoplasm affecting the brain. "Clinically approved HH/GLI pathway inhibitors target the essential pathway effector Smoothened (SMO) with striking therapeutic efficacy in skin and brain cancer patients." (PMID 30991683, 2019). "Despite showing impressive therapeutic activity in nonmelanoma skin cancer, brain cancer, and AML, frequent and rapid resistance development urgently calls for the next generation of HH pathway inhibitors able to block both wild-type and mutant SMO proteins." (PMID 30991683, 2019).
cerebral infarction (1 paper, 2022). An ischemic condition of the brain, producing a persistent focal neurological deficit in the area of distribution of the cerebral arteries. "Apart from that, the application of SMO-specific antagonist NVP-LDE225 can effectively relieve cerebral infarction and improve neurological function, suggesting that SMO may be a potential therapeutic target." (PMID 36012647, 2022).
Chordoid Meningioma (1 paper, 2022). A WHO grade II, usually recurring meningioma characterized by the predominance of tissues that are histologically similar to chordoma. "Genetically, previous studies found that chordoid meningiomas had sparce NF2, TRAF7, KLF4, SMO, AKT1 and SMARCB1 mutations common to non-chordoid meningioma." (PMID 35440040, 2022). "Chordoid meningiomas were enriched in mutations in chromatin remodeling genes EP400 (8/11,73%) KMT2C (4/11, 36%) and KMT2D (4/11, 36%), and showed low or absent NF2, TERT, SMO, and AKT1 mutations." (PMID 35440040, 2022).
Cirrhosis (1 paper, 2017). A chronic disorder of the liver in which liver tissue becomes scarred and is partially replaced by regenerative nodules and fibrotic tissue resulting in loss of liver function. "In the experimental thioacetamide (TAA) model of cirrhosis, we recently demonstrated that canonical Hh/Pc/SMO/GLI-mediated signaling amplifies the LPC response." (PMID 28187190, 2017). "Importantly, current trials have selected an anti-SMO inhibitor (LDE225) for cirrhosis treatment; however, our results suggest that GLI (either with or without combinatorial targeting of SMO) may be a more appropriate signaling node within the Hh pathway to target." (PMID 28187190, 2017).
colitis (1 paper, 2022). Inflammation of the colon. "Conversely, activation of the pathway in stroma by partial Ptch1 loss or treatment with the SMO agonist SAG21k ameliorated the DSS-induced colitis with increased IL-10 expression and increased CD4+ Foxp3+ regulatory T cells." (PMID 36010600, 2022). "Furthermore, loss of stromal pathway by genetic Smo deletion or treatment with XL-139 (a SMO antagonist) worsened DSS-induced inflammation and colitis." (PMID 36010600, 2022).
craniosynostosis (1 paper, 2022). Craniosynostosis is defined as the premature fusion of one or more cranial sutures leading to secondary distortion of skull shape resulting in skull deformities with a variable presentation. "More recently, mutations in Zic family member 1 (ZIC1); SMAD family member 6 (SMAD6); HECT, UBA and WWE domain-containing 1, E3 ubiquitin protein ligase (HUWE1); and smoothened, frizzled class receptor (SMO) have been identified as causal in the development of craniosynostosis." (PMID 35451466, 2022).
cutaneous leishmaniasis (1 paper, 2018). Leishmaniasis affecting the skin. "Interestingly, SMO pretreatment was more potent than pentostam, a standard drug for cutaneous leishmaniasis." (PMID 29786651, 2018).
diffuse large B-cell lymphoma (1 paper, 2022). "The latest study has indicated that SMO is involved in the regulation of the oncogenic IGF1R/AKT signaling axis and is unrelated to canonical Hedgehog signaling in diffuse large B-cell lymphoma (DLBCL)." (PMID 36405701, 2022).
ductal carcinomas (1 paper, 2019). "It is possible, then, that the upregulation of SMO observed in 70% of ductal carcinomas and 30% of TNBCs, makes those tumors sensitive to Hh pathway activation by dietary oxysterols." (PMID 31027259, 2019). "In agreement with the in vitro and animal studies findings, biopsies of ductal carcinomas showed an inverse correlation of the expression level of LKB1 with SHH, GLI1 and SMO." (PMID 31027259, 2019).
endometriosis (1 paper, 2022). The growth of functional endometrial tissue in anatomic sites outside the uterine body. "SHH, SMO, GLI1 and GLI3 expression was strongly increased with clinical stages in the eutopic endometrium, which suggested that the SHH signaling pathway was abnormally activated in endometriosis." (PMID 35933378, 2022).
esophageal squamous cell carcinoma (1 paper, 2025). Esophageal squamous cell carcinoma (ESCC) is a type of esophageal carcinoma (EC) that can affect any part of the esophagus, but is usually located in the upper or middle third. "The overexpression of ATAD2 induces the production of the HH pathway proteins (SHH, SMO, GLI, and PTCH1) in Rb and esophageal squamous cell carcinoma cells (ESCC), which in turn promotes invasion, migration, and proliferation." (PMID 41154392, 2025).
esophagitis (1 paper, 2016). An acute or chronic inflammatory disease affecting the esophageal wall. "Two SNPs (rs1061280 and rs1061285) in the SMO gene were also identified as significantly associated with the risk of esophagitis after multiple comparison corrections." (PMID 26991123, 2016). "Patients with the AG+GG genotype of SMO:rs1061280 had an 81% reduced risk of developing esophagitis (OR: 0.19, 95% CI: 0.07–0.53, p = 0.001, q = 0.06)." (PMID 26991123, 2016). "After multiple comparison corrections, three SNPs (RPS6KB2:rs10274, SMO:rs1061280, SMO:rs1061285) remained significantly associated with esophagitis (q<0.1)." (PMID 26991123, 2016). "After multiple comparison correction, RPS6KB2:rs10274, SMO:rs1061280, SMO:rs1061285 remained significantly associated with esophagitis, while processing gene DGCR8:rs720014, DGCR8:rs3757, DGCR8:rs1633445 remained significantly associated with pneumonitis." (PMID 26991123, 2016). "Patients with AG+GG genotype of SMO:rs1061280 (in high LD with SMO:rs1061285, r2>0.8) had an 81% reduced risk of developing esophagitis (OR: 0.19, 95% CI: 0.07–0.53, p = 0.001, q = 0.06)." (PMID 26991123, 2016). "Our data suggest that the AKT/mTOR and SMO-Hh pathway probably contribute to radiotherapy-induced esophagitis, while the AKT pathway probably contributes to the pneumonitis." (PMID 26991123, 2016). "It is likely that the binding site SNPs (SMO: rs1061280, SMO: rs1061285) could affect SMO gene transcription or functions that contribute to the etiology of esophagitis after radiotherapy." (PMID 26991123, 2016).
fibrosis (1 paper, 2026). the formation of excess fibrous connective tissue in an organ or tissue in a reparative or reactive process. "Thus, beyond its association with the CK2α/SMO interaction, miR-55 exhibits a pleiotropic regulatory advantage by improving redox homeostasis, providing a more comprehensive mechanistic basis for its therapeutic potential against MAFLD-related fibrosis." (PMID 41596397, 2026).
germ cell cancer (1 paper, 2020). "The presence of higher copies of SMO and SHH, in addition to lower copy numbers of PTCH1 (which inhibits SMO activity) in germ cell tumors are another supporting fact of the involvement of HH signaling in germ cell cancer formation." (PMID 32245491, 2020).
glioneuronal tumors (1 paper, 2018). "Identical DEPDC5 and SMO E3 SNP also occurred in all FCD type II samples and the majority of glioneuronal tumors, while the other common SNPs did not occur in all FCD or glioneuronal tumors." (PMID 28833756, 2018).
hematoma (1 paper, 2020). A hematoma is a collection of blood from a vascular structure into an extravascular space. "Compared with the vehicle-treated group, the hematoma sizes in mice injected with SMO inhibitors were significantly increased at day 3 after ICH surgery." (PMID 33343302, 2020). "The inhibition of the SHH signaling pathway using SMO inhibitors treatment aggravated neurological impairments, brain edema, hematoma volume, and BBB permeability in the early stage of ICH in mice." (PMID 33343302, 2020).
hyperplastic (1 paper, 2021). "The expression levels of SMO cascade were upregulated in the human hyperplastic prostate and BPH rat prostate when compared with normal controls." (PMID 34006832, 2021). "In the hyperplastic prostate, the mRNA level of SMO and GLI1–3 was significantly increased over 2-fold and the protein level of these molecules was consistently increased." (PMID 34006832, 2021).
Hypokalemia (1 paper, 2019). An abnormally decreased potassium concentration in the blood. "A total of 320 cases received SMO inhibitor therapy and 36 cases reported grade 3/4 DLT, including γ-glutamyl transferase, hypokalemia and thrombocytopenia." (PMID 31362788, 2019).
keloid (1 paper, 2023). An irregularly shaped, elevated mark on the skin caused by deposits of excessive amounts of collagen during wound healing. "However, the mechanism by which SMO mRNA expression is higher in NS than in stem-like cells of keloid patients has not been elucidated." (PMID 38062202, 2023).
kidney cancer (1 paper, 2020). Primary or metastatic malignant neoplasm involving the kidney. "The highest expression of SMO was found in ovary, followed by lung and kidney cancer cell lines." (PMID 32784501, 2020).
Lowe syndrome (1 paper, 2020). "Similar to Inpp5e-null cells, fibroblasts from the Lowe syndrome mouse model exhibit reduced SAG-stimulated SMO ciliary localisation." (PMID 32970140, 2020).
medullary thyroid cancers (1 paper, 2022). "In addition, blockade of hedgehog signaling pathway by SMO antagonist also inhibited cell viability, inducing apoptosis in medullary thyroid cancers." (PMID 35406554, 2022).
metastatic melanoma (1 paper, 2013). A melanoma that has spread from its primary site to another anatomic site. "Although other groups have reported upregulation of hedgehog pathway members in metastatic tissue as compared to primary specimens, this is the first report of an association of SMO levels with significantly decreased survival in metastatic melanoma patients." (PMID 24287465, 2013). "Finally, increased SMO expression and decreased expression of the hedgehog pathway repressor GLI3 correlated with shorter post recurrence survival in metastatic melanoma patients." (PMID 24287465, 2013).
myelofibrosis (1 paper, 2022). A partial or complete replacement of the bone marrow stroma by fibrous tissue. "Two other SMO inhibitors IPI-926 (Sardegib) and BMS-833923 were studied in myelofibrosis and CML, respectively." (PMID 36091167, 2022).
myxofibrosarcoma (1 paper, 2013). A malignant fibroblastic neoplasm arising from the soft tissue. "Typically, myxofibrosarcoma gain and/or amplification was mapped to 7p21.3-q31.1, q31.1-q31.33, q33-q36.2, p21.3, p21.2, p14.1-q11.23, q31.33-q33, p21.2-p14.1, q11.23-q21.3, q36.2-q36.3, which, respectively are known to harbour tumour-associated genes, including TIF, BRAF, MLL3, SMO, and MET." (PMID 24289252, 2013).
Obesity (1 paper, 2023). Accumulation of substantial excess body fat. "Genetic ablation of GLI2 or SMO in mice implies defective Hh signaling pathway that results in obesity, but, physiologically, whether dysregulated Hh signaling contributes to hypertrophic obesity warrants further investigation, in particular the missing link with ASCs and preadipocyte commitment." (PMID 36831329, 2023).
oral cancer (1 paper, 2025). "The PRKD1 E710D hotspot mutation and protein expression of PRKD1 and HH components (SHH, IHH, SMO, and GLI‐1) were detected in PAC regardless of tissue invasion, although HH proteins contributed to the morphogenesis of this rare oral cancer." (PMID 40930949, 2025).
oral squamous cell carcinoma (1 paper, 2020). "In the context of oral squamous cell carcinoma, disease severity has been positively correlated with the canonical activation of the Hedgehog pathway, occurring independently of PTCH1/SMO complex signaling." (PMID 32846867, 2020).
pancreatic adenocarcinoma (1 paper, 2011). "MS-0022 was identified as a potent antagonist of Hh signaling that blocks the translocation of SMO to the cilia displaying a transient in vivo antagonistic effect in a pancreatic adenocarcinoma xenograft model." (PMID 21698280, 2011).
paraganglioma (1 paper, 2022). A benign or malignant neoplasm arising from paraganglia located along the sympathetic or parasympathetic nerves. "All cancers expressed SMO, with the highest levels in kidney renal papillary cell carcinoma (KIRP) and the lowest levels in pheochromocytoma and paraganglioma (PCPG)." (PMID 36405701, 2022).
parasite infections (1 paper, 2025). "Our GO enrichment analysis shows that response to stimulus is the most significantly enriched biological process, which is highly consistent with host immune response mechanisms triggered by parasite infections, in which the core genes TNF, STAT3, STAT5A, PDGFB, ADRB2 and SMO were included." (PMID 41153368, 2025).
Rhabdoid Meningioma (1 paper, 2022). A WHO grade III meningioma characterized by the predominant presence of rhabdoid cells forming sheets. "In this regard, SMO, AKT, and PIK3CA mutations are typical of anterior skull base meningiomas, whereas KLF4 mutations are specific for secretory histology, and BAP1 alterations are common in progressive rhabdoid meningiomas." (PMID 35565385, 2022).
skull base tumors (1 paper, 2025). "Genotype (p = 0.004) and WHO grade (p = 0.002) were significantly associated with tumor location: NF2 alterations predominated in convexity and spine, while TRAKLS mutations (TRAF7, AKT1, KLF4, SMO) were enriched in lower-grade skull base tumors." (PMID 40951339, 2025).
Smith-Lemli-Opitz syndrome (1 paper, 2016). Smith-Lemli-Opitz syndrome (SLOS) is characterized by multiple congenital anomalies, intellectual deficit, and behavioral problems. "Impaired SMO activation caused by cholesterol deficiency has also been noted in Smith-Lemli-Opitz syndrome (SLOS), a congenital malformation syndrome caused by defects in the enzyme that converts 7-dehydrocholesterol to cholesterol." (PMID 27705744, 2016).
Splenomegaly (1 paper, 2019). Abnormal increased size of the spleen. "• The SMO inhibitor sonidegib when used in conjunction with ruxolitinib showed a significant reduction in splenomegaly in approximately two-thirds of patients with PMF in a phase I study." (PMID 31244289, 2019).
steatosis (1 paper, 2016). Increased lipid within the cytoplasm of cells. "In addition to these results in vivo, the inhibition of Hh signaling in cultured mouse and human hepatocytes using the SMO inhibitor cyclopamine also resulted in marked steatosis within 48 to 72 hr." (PMID 27185526, 2016).
synovial sarcoma (1 paper, 2020). "Several other genes pertaining to these networks may be dysregulated in synovial sarcoma, including LEF1, AXIN2, TCF7, and FZD homologues in the Wnt/β-catenin, HES1, and NOTCH1 in the Notch, as well as SMO and PTCH in the Sonic Hedgehog pathways." (PMID 32322158, 2020).
thyroid tumor (1 paper, 2021). A benign or malignant neoplasm affecting the thyroid gland. "Our recent study showed that the inhibitors of the Shh pathway such as cyclopamine (CP), a Smothened (SMO) inhibitor, and GANT61, a Gli1 inhibitor, have modest inhibitory effects on thyroid tumor cell proliferation and tumor growth." (PMID 33966040, 2021).
ulcerative colitis (1 paper, 2022). An inflammatory bowel disease involving the mucosal surface of the large intestine and rectum. "We chose two large cohorts of patients with ulcerative colitis and found significant upregulation of SMO and GLI3 in ulcerative colitis patients compared to healthy controls." (PMID 35835905, 2022).
urothelial carcinoma (1 paper, 2023). A malignant neoplasm derived from the transitional epithelium of the urinary tract (urinary bladder, ureter, urethra, or renal pelvis). "As per findings of a few studies, dysregulation of SHH ligand or one of its downstream mediators, for instance, PTCH1, SMO, or GLI1, has been linked to urothelial carcinoma initiation and progression and in modulating cancer stem cell activities." (PMID 37069207, 2023).